CBX1 (chromobox 1)
Diseases named in the same sentence as CBX1 in open-access papers (continued):
Sharing a sentence is not in itself a finding about the gene and the disease.
nasopharyngeal carcinoma (2 papers, 2022 to 2025). A carcinoma arising from the nasopharyngeal epithelium. "m6A methylomes are mapping in nasopharyngeal carcinoma (NPC) using m6A sequencing, and CBX1 is identified to be significantly upregulated with m6A hypomethylation in metastatic NPC tissues." (PMID 36310139, 2022). "Chromobox 1 (CBX1), a histone methylation regulator, has been identified as significantly upregulated with m6A hypomethylation in metastatic nasopharyngeal carcinoma (NPC) tissues." (PMID 39987091, 2025).
thyroid carcinoma (2 papers, 2020 to 2022). "However, CBX1 was also reported as being downregulated and contributing to tumor progression in thyroid carcinoma." (PMID 36140750, 2022).
Clear cell renal cell carcinoma (1 paper, 2023). "Conversely, in Clear cell renal cell carcinoma patients, the Kaplan–Meier curve analysis revealed that high expression of CBX1 was significantly correlated with better OS and disease-free survival." (PMID 37430195, 2023).
Cockayne syndrome-B (1 paper, 2014). "TFII-I interacted with genes encoding for the heme-regulated eIF2α kinase HRI (EIF2AK1), the Cockayne syndrome-B (CS-B or ERCC6), heterochromatin protein 1 beta (Hp1 beta, CBX1) and TF ATF3." (PMID 24875474, 2014).
endometrial tumors (1 paper, 2022). "As for CBX1 and CBX2—we observed positive association with cancer stemness in liver, lung and endometrial tumors, while CBX4, CBX5, CBX6, and CBX8 exhibit rather weak correlation with cancer stemness in a tumor-specific manner." (PMID 36361869, 2022).
gastric intestinal type adenocarcinoma (1 paper, 2020). An adenocarcinoma of the stomach arising on a background of intestinal metaplasia. "In D'Errico's gastric dataset, CBX1 was found to be upregulated in gastric intestinal-type adenocarcinoma (fold − change = 2.116 and P = 2.21E − 13)." (PMID 33344640, 2020).
Infertility (1 paper, 2020). "CBX5, CBX1 and CBX3 null mutant mice revealed different phenotypic outcomes for the three isoforms: CBX5−/− mice presented a normal phenotype, CBX1−/− led to perinatal lethality, and CBX3−/− to infertility." (PMID 32545538, 2020).
liver cirrhosis (1 paper, 2025). "Several CBX1-related miRNAs have been implicated in liver cirrhosis, including hsa-miR-494-3p, hsa-miR-29c-3p, hsa-miR-145-3p, hsa-miR-159d-3p, hsa-miR-126-5p, hsa-miR-92a-3p, hsa-miR-185-5p, and hsa-let-7a-5p." (PMID 40572671, 2025).
pancreatic cancer (1 paper, 2022). "It is worth noting that the mRNA levels of CBX1, CBX3, CBX5 and CBX8 were elevated in pancreatic cancer tissues compared with non-malignant pancreatic tissues." (PMID 35637952, 2022). "Bioinformatic analyses through the GEPIA web tool revealed that CBX3, CBX1, and CBX5 were significantly overexpressed in the pancreatic cancer tissues than those in non-malignant pancreatic tissues (P < 0.01)." (PMID 35637952, 2022).
rectal adenocarcinoma (1 paper, 2021). "Consistent with the Oncomine database, CBX1-5 and CBX8 transcripts in colon and rectal adenocarcinoma tissues were higher than in normal tissues." (PMID 34321009, 2021).
rectal cancer (1 paper, 2020). A primary or metastatic malignant neoplasm that affects the rectum. "The expression of CBX1 was in connection with the infiltration of CD4+ T cells, neutrophils, B cells, CD8+ T cells, macrophages, and dendritic cells in colon and rectal cancers." (PMID 33014884, 2020).
serous ovarian carcinoma (1 paper, 2020). "In summary, our results showed that the CBX1, CBX2 and CBX3 proteins were overexpressed in serous ovarian carcinoma tissues compared with normal ovarian tissues." (PMID 32742466, 2020). "Thus, the CBX1 and CBX2 mRNA levels in serous ovarian cancer patients were related to poor OS and PFS, and CBX3 mRNA was related to poor OS." (PMID 32742466, 2020). "Finally, the expression levels of CBX1 and CBX2 at the transcriptional level in serous ovarian cancer patients were related to poor OS and PFS, and CBX3 was associated with poor OS." (PMID 32742466, 2020).
cancer (39 papers, 2016 to 2025). A tumor composed of atypical neoplastic, often pleomorphic cells that invade other tissues. "The biological functions and prognostic significance of CBX1-8 in cancer progression remain uncertain, with misregulation of CBX proteins being linked to various cancer types." (PMID 40806514, 2025). "Background and Objectives: Chromobox 1 (CBX1), a key epigenetic regulator involved in chromatin remodeling, has been implicated in various cancers; however, its role in liver hepatocellular carcinoma (LIHC) remains underexplored." (PMID 40572671, 2025). "Expression of CBX1/2/3/5 mRNA was significantly associated with each patient’s cancer stage, suggesting that it be playing a crucial role in HCC progression." (PMID 35677563, 2022). "Low CBX1 levels are associated with advanced cancer stage and tumor grade." (PMID 34395271, 2021). "Differential expression of CBX1 between tumor and normal tissues from various cancer types, including LIHC, was analyzed using the GEPIA2 database." (PMID 40572671, 2025). "CBX1 promotes cancer proliferation by interacting with SUV39H1 to enhance H3K9 trimethylation and subsequent transcriptional silencing of tumor suppressor genes." (PMID 40175347, 2025). "We also observed that several CBX members are frequently amplified in cancer tissues, especially CBX1, CBX2, CBX3, CBX4, and CBX8 in LUAD and LIHC tumors." (PMID 36361869, 2022). "We compared the mRNA expression of the CBXs in cancer and normal samples using the Oncomine database and found that the transcriptional levels of CBX1/2//3/4/5/8 were upregulated while that of CBX6/7 were downregulated in majority of the cancers." (PMID 33344640, 2020). "In general, CBX1/2/3/4/5/6/8 are tumor promoting factors in most cancers, and CBX7 is tumor-suppressing factor in almost all cancers, thus CBXs could serve as diagnostic and prognostic biomarkers." (PMID 40302984, 2025). "Specifically, CBX1 and CBX3 play a crucial role in heterochromatin formation, gene silencing, and DNA damage response and have been implicated in various cellular processes, including cell cycle regulation and cancer progression." (PMID 40175347, 2025). "The up-regulated expression of HP1-β (CBX1) has been reported for many forms of cancer." (PMID 34046352, 2021). "Eight members of the CBX clan, CBX1/2/3/4, were significantly expressed at a high level, whereas CBX6/7 was significantly downregulated in most cancer types, such as BLCA." (PMID 37189494, 2023). "The expression of CBX1, CBX2, CBX5, and CBX8 significantly positively correlates with cancer stemness in LIHC, LUAD, and UCEC tumors, while CBX6—negatively associates with cancer stemness in LUAD and PAAD tumors." (PMID 36361869, 2022). "Among the 8 CBXs family members, the expression levels of CBX1/3 were significantly upregulated, whereas CBX7 expression was significantly downregulated in other cancer types." (PMID 35969177, 2022). "The upregulation of the mRNA of CBX1/2/3/4/5/8 and downregulation of CBX7 were found to be significantly correlated to the nodal metastatic status and individual cancer stage in GC patients." (PMID 33344640, 2020). "For instance, three isoforms of HP1 (CBX1, CBX3, and CBX5) act as organizers of pericentric heterochromatin in conjunction with H3K27me3, which hinders cell cycle progression, leading to transcriptional activation, cell proliferation and cancer." (PMID 34321009, 2021). "Investigation of TCGA (The Cancer Genome Atlas) data set revealed that while Cbx1 and Cbx5 are not regulated, Cbx3 is upregulated in GBM compared to control brain samples, although not due to differential methylation." (PMID 27291091, 2016). "Moreover, the mRNA expression levels of CBX1/3/6 had a trend to lower expression in more advanced cancer stages, although that was not statistically significant." (PMID 35155439, 2022).
cancer (continued). "Besides, the mRNA expression levels of CBX1/3/6 showed a significant difference in OV tissues compared to normal tissues, however, their expression levels only had a trend to lower expression in more advanced cancer stages but without statistical significance." (PMID 35155439, 2022).
tumor (36 papers, 2012 to 2025). "Except for CBX7, the mRNA levels of CBX1/2/3/4/5/6//8 was all significantly associated with tumor recurrence status." (PMID 35210369, 2022). "High expression of CBX1 is significantly associated with a large tumor size, tumor vascular invasion, poor tumor differentiation, and prognosis in HCC patients." (PMID 34395271, 2021). "High CBX1 expression was significantly associated with larger tumor size, poor tumor differentiation and tumor vascular invasion." (PMID 30717368, 2019). "High CBX1 expression was associated with larger tumor size, poor tumor differentiation, tumor vascular invasion and unfavorable OS and DFS in HCC cases." (PMID 30481161, 2018). "The analysis revealed statistically significant correlations between CBX1 expression and primary tumor, tumor stage (I–III), tumor grade (I–IV), and histological subtype." (PMID 40572671, 2025). "Our findings indicated that CBX1/3/8 are tumor promoters, while CBX7 serves as a tumor suppressor in ESCA." (PMID 35464847, 2022). "Patients who were in more advanced tumor nodal metastasis status tended to express higher mRNA of CBX1." (PMID 35464847, 2022). "MRNA expressions of CBX1, CBX2, CBX3, CBX4, and CBX8 were significantly associated with tumor grades." (PMID 35464847, 2022). "CBX1 expression was increased in the advanced stage (stage II/III) as compared with those in the early tumor stage (stage I)." (PMID 35464847, 2022). "The expression of CBX1 tended to be higher as the tumor stage increased, which was consistent with the previous findings in the GEPIA database." (PMID 35464847, 2022). "CBX1 protein expression was obviously elevated in tumor specimens (6.54 ± 0.32) compared with normal ovarian tissues (4.14 ± 0.29, P < 0.01)." (PMID 32742466, 2020). "The highest mRNA expressions of CBX1/3/4/5/6/8 were found in tumor grade 4, while the highest mRNA expression of CBX2 was found in grade 3." (PMID 30481161, 2018). "Consequently, decreased YTHDF3 levels in NPC lead to increased CBX1 expression, promoting tumor progression." (PMID 39695216, 2024). "In NPC, YTHDF3 destabilizes m6A-modified CBX1 mRNA, acting as a tumor suppressor." (PMID 39695216, 2024). "Notably, our study found that DLBCL cells with CBX1 over-expression were resistant to the common anti-tumor drugs, but CBX2/5 had two polarities." (PMID 37430195, 2023). "The results showed that knockout of CBX1 significantly inhibited the growth of MC38 tumor." (PMID 36310139, 2022). "Furthermore, the results from the subcutaneous xenograft model showed that knocking out CBX1 significantly inhibited tumor growth and that tumor tissues in the CBX1‐knockout group had lower expression of Ki67 and PCNA than those in the sgNC group." (PMID 36310139, 2022). "In addition, the proportion of tumor‐infiltrating CD8+ T cells as well as TNFα+ CD8+ T cells was significantly increased in Cbx1‐knockout tumors, indicating the enhanced CD8+ T‐cell antitumor immune response in Cbx1‐knockout tumors." (PMID 36310139, 2022). "Moreover, CBX1/3/4/5/8 was significantly upregulated in tumor, relative to normal tissues, which was consistent with the trend of expression observed in the TGCA database." (PMID 35677563, 2022). "CBX1, CBX6, and CBX7 were also significantly associated with the tumor stage." (PMID 36292141, 2022). "Moreover, the expression of MAP7 was negatively correlated with CBX1 expression in tumor tissues from a subcutaneous xenograft mouse model." (PMID 36310139, 2022).
tumor (continued). "CBX1 functions as an oncogene and promote tumor progression in liver cancer." (PMID 34001881, 2021). "Notably, several hyper- and hypomethylated probes were associated with poor survival outcomes, suggesting that epigenetic dysregulation of CBX1 may contribute to tumor progression and serve as a prognostic indicator in LIHC." (PMID 40572671, 2025). "The CBX1 expression levels in HCC and adjacent non-tumor tissues were quantified through Real-Time Polymerase Chain Reaction (RT-PCR), Western Blotting (WB), and Immunohistochemical analyses." (PMID 38769286, 2024). "Taken together, these data suggested that the mRNA overexpression of CBX1, CBX3, and CBX8 were significantly related to tumor grades and patients’ tumor nodal metastasis status." (PMID 35464847, 2022). "Contrary to the pro-tumor effect assessed in HCC, here, we disclosed a potential antitumor effect of CBX1 in ccRCC, consistent with recent results reported by Zhu and colleagues." (PMID 36292141, 2022). "Our findings indicated that CBX1 and CBX8 mRNAs were significantly upregulated in HCC tumor, relative to adjacent normal, tissues." (PMID 35677563, 2022). "The mRNA expression of CBX1, CBX2, CBX3, CBX4, and CBX8 tended to be elevated as the tumor grade increased." (PMID 35464847, 2022). "We used GEPIA to compare expression levels of CBX mRNAs between HCC (n = 369) with normal adjacent liver (n = 160) tissues and found that CBX1 and CBX8 were significantly upregulated in tumor, relative to normal tissues." (PMID 35677563, 2022). "We observed significant positive correlation between a high CBX1, CBX2, CBX3, CBX5, and CBX8 expression and higher tumor grade in LIHC and UCEC tumors." (PMID 36361869, 2022). "Specifically, we observed significant upregulation of CBX1, CBX3, and CBX5 members, followed by robust downregulation of CBX7 in tumor tissues." (PMID 36361869, 2022). "As the tumor progressed, patients with more advanced tumor grades tended to express higher mRNA expression of CBX3 and CBX4 but lower mRNA expression of CBX1, CBX5, CBX6, and CBX7." (PMID 34395271, 2021). "This possibility has been confirmed by numerous studies.109110 However, m6A on CBX1 mRNA decreases its stability via YTHDF3 recognition, and CBX1 upregulates PD-L1 expression via the IFN-γ-STAT1 pathway, suggesting diverse functions of m6A in tumor immunity." (PMID 37485079, 2023). "Through literature review and analysis, we have found that the role of CBX1 in tumor development is not clear." (PMID 37430195, 2023). "The mRNA levels of CBX2/3/6/7/8 were related to tumor grades, but the mRNA expressions of CBX1/4/5 were not markedly different." (PMID 35210369, 2022). "Similarly, mRNA expressions of CBX1, CBX2, CBX3, CBX4, and CBX8 were significantly related to patients’ tumor nodal metastasis status." (PMID 35464847, 2022). "The expression of CBX genes differs across solid tumors and for CBX1, CBX2, CBX3, CBX4, CBX5, and CBX8 is predominantly upregulated, while for CBX6 and CBX7 is mostly downregulated in tumor tissues." (PMID 36361869, 2022). "As immunosuppressive molecules (e.g., PD‐L1, IDO1, and IL‐18BP) that can be induced by interferon‐gamma (IFN‐γ) are generally important to facilitate immune evasion by tumor cells, we wondered whether the expression of these immunosuppressive molecules in NPC cells is affected by CBX1." (PMID 36310139, 2022). "We also revealed a significant positive correlation of CBX1 and CBX5 with tumor dedifferentiation status, although not in all tested tumor types." (PMID 36361869, 2022). "Although without a net trend, the mRNA expression distribution of CBX1 in clear cell subtypes and CBX6 in both subtypes were significantly different among tumor stages." (PMID 36292141, 2022).
neurodevelopmental disorder (1 paper, 2024). A behavioral and cognitive disorder with onset during the developmental period that involves impaired or aberrant development of intellectual, motor, or social functions. "Similarly, a recent study confirmed that mutation in the CBX1 gene could cause a novel syndromic neurodevelopmental disorder in mice." (PMID 39227733, 2024).
psychiatric disorder (1 paper, 2025). A disorder characterized by behavioral and/or psychological abnormalities, often accompanied by physical symptoms. "Regarding the protein CBX1, given its role in epigenetic regulation, it is possible that this protein could indirectly influence psychiatric disorders like BD through its effects on gene expression." (PMID 41013196, 2025).
CBX1 also shares sentences with these, for which no sentence is quoted: colorectal cancer (4 papers); infection (2); lung adenocarcinoma (2); lymph node metastasis (2); Obesity (2); pancreatic adenocarcinoma (2); viral infection (2); acute myeloid leukemia (1); Anxiety (1); bladder cancer (1); cerebral infarction (1); cholangiocarcinoma (1); fibrosarcoma (1); HCMV Infection (1); Hutchinson-Gilford progeria syndrome (1); Hyperoxaluria (1); Hypertension (1); leiomyosarcoma (1); leukemia (1); liver disease (1); lung squamous cell carcinoma (1); malignant fibrous histiocytoma (1); metastasis (1); paraganglioma (1); Paralysis (1); pheochromocytoma (1); pituitary cancer (1); pleomorphic liposarcoma (1); renal cell carcinoma (1); steatosis (1).
A further 3 diseases each share a sentence with CBX1 in 1 paper.